SAXO3 (stabilizer of axonemal microtubules 3)
Synonyms: FAP257
Gene: Protein-coding gene on chromosome 19 (49,017,968 to 49,020,549, reverse strand). Ensembl gene ENSG00000268655.
Genetic constraint (gnomAD): Loss-of-function variants: 7 observed, 6.14 expected, observed/expected ratio (o/e) 1.14, 90% interval 0.64 to 1.84. That is too few expected variants to judge how well the gene tolerates losing a copy. Missense variants: 88 observed, 84.83 expected, observed/expected ratio (o/e) 1.04, 90% interval 0.87 to 1.24. Synonymous variants: 40 observed, 36.98 expected, observed/expected ratio (o/e) 1.08, 90% interval 0.84 to 1.41.
Homologues: Orthologues: chimpanzee SAXO3 (97% identical), macaque SAXO3 (89% identical), pig SAXO3 (75% identical), rat Lhb (55% identical), mouse Lhb (53% identical).